BCL2 (BCL2 apoptosis regulator)
Diseases named in the same sentence as BCL2 in open-access papers (continued):
Sharing a sentence is not in itself a finding about the gene and the disease.
glioblastoma (continued). "In recurring glioblastomas, an overexpression of Bcl-2, Bcl-xL, and Mcl-1, and a downregulation of pro-apoptotic proteins like Bax, Bak, Bok, and NOXA have been observed." (PMID 30486451, 2018). "Upregulation of the anti-apoptotic proteins Bcl-2 and Bcl-XL have been reported to contribute to the recurrence of glioblastomas, accompanied with the downregulation of pro-apoptotic Bax." (PMID 29977208, 2018). "We found that combined treatment with ABT263 and Crizotinib synergistically reduces the proliferation of glioblastoma cells, which was dependent on dual inhibition of Bcl-2 and Bcl-xL." (PMID 29743557, 2018). "In glioblastoma T98G cells, berberine inhibits the activity of Bcl-2, increasing the levels of Bax, caspase-9, and caspase-3." (PMID 30486451, 2018). "Knockdown of PKCε markedly enhanced the protein expression of Bcl-2 in both glioblastoma cell lines." (PMID 29439667, 2018). "TRAIL induces apoptosis even when Bcl-2 is overexpressed in the tumor, since the former activates caspase-8, Bid, and caspase-9 in glioblastoma LN-229 cells when cultured with TRAIL." (PMID 30486451, 2018). "The compound-1H has the potential to induce apoptosis by up-regulating Bax, cleaved caspase-9, cleaved caspase-3, and cleaved PARP and down-regulating Bcl-2 protein levels in glioblastoma cells." (PMID 29988358, 2018). "Up-regulation of anti-apoptotic Bcl-2 and Bcl-XL expression contributes to glioblastoma recurrence, in parallel with down-regulation of the pro-apoptotic protein Bax." (PMID 30587839, 2018). "Anti-apoptotic proteins like Bcl-2, Bcl-xL, and Mcl-1 are often overexpressed in glioblastoma, allowing cellular proliferation and the resistance of tumor cells to various therapies." (PMID 30486451, 2018). "A further challenge in treating glioblastoma is its intrinsic resistance to apoptosis, through the overexpression of anti-apoptotic proteins such as Bcl-2, and other mechanisms." (PMID 29113289, 2017). "This is further supported by findings that Usp9x knockdown recapitulated the apoptotic effects of CP-d/n-ATF5-S1 and also led to downregulation of BAG3, MCL1, and BCL2 in various glioblastoma cell lines." (PMID 29137451, 2017). "U87MG and murine glioblastoma cells bearing the IDH1 mutation showed decreased expression of Mcl-1, Bcl-xL, and Bcl-2." (PMID 29057925, 2017). "Here, we used four established glioblastoma cell lines and two primary glioblastoma cell lines that express the antiapoptotic proteins Bcl-2, Bcl-xL, and Mcl-1, but showed different sensitivity to IR-induced apoptosis." (PMID 26775694, 2016). "MiR-10b decreased radiation-induced apoptosis in glioblastoma cells by activation of caspase 3/7 and inhibition Bcl-2 expression." (PMID 27347488, 2016). "All four glioblastoma cell lines expressed USP9x as well as antiapoptotic Mcl-1, Bcl-2, Bcl-xL, and pro-apoptotic Bax, Bak, Noxa, Puma, and Bad." (PMID 26775694, 2016). "In particular, miR-21 has been reported to protect glioblastoma cells from the chemotherapeutic drug temozolomide-induced apoptosis by decreasing the Bax/Bcl-2 ratio and caspase-3 activity." (PMID 26928365, 2016). "Analysis by synthesis, we concluded that the proapoptosis signaling way of SFN in U251MG glioblastoma cells was SFN–Bad–Bax/Bcl-2-cytochrome C-caspases." (PMID 27026929, 2016). "Overall, these observations confirm that drug combination therapies, involving Bcl-2/Bcl-xL inhibition, are potentially feasible for the treatment of glioblastoma." (PMID 26474387, 2015). "Here, we describe a novel drug combination for the treatment of glioblastoma that consists of the orally available Bcl-2/Bcl-xL inhibitor ABT263 and the Mcl-1 inhibitor GX15-070." (PMID 26008975, 2015). "Our data confirms the previous notion that knocking down Usp9X suppresses Mcl-1 along with Bcl-2 and primes glioblastoma cells to ABT263." (PMID 26474387, 2015).
glioblastoma (continued). "Overall, TIC10/ONC201 along with Bcl-2/Bcl-xL inhibition holds significant promise as a novel potential approach for the treatment of recalcitrant tumors such as glioblastoma." (PMID 26474387, 2015). "In case of glioblastoma cells 8 mM of asprin reduced Bcl-2 expression to 42% after 48 hrs whereas only 0.33 mM NA-2 inhibited Bcl-2 expression to approximately 35% as compare to control which was increased to 96% when given in combination with TMZ." (PMID 25663820, 2014). "Cathepsin B is rather prominently upregulated in glioblastoma and promotes glioblastoma growth by contributing to matrix dissolution, Bcl-2 maintenance, and AKT activation." (PMID 25211298, 2014). "As increased autophagy and apoptosis were observed in both the combination and triple treatment, we related these effects to altered levels of the anti-apoptotic Bcl-2 proteins Bcl-XL and Mcl-1 in the patient-derived glioblastoma culture GS257." (PMID 25568669, 2014). "We emphasize the functional relation between Bcl-2 proteins and radiosensitization by HDACi and provide a target for increasing responsiveness in glioblastoma by using the Bcl-2 inhibitor Obatoclax." (PMID 25568669, 2014). "Shh inhibitors (which downregulate BCL2) are currently being investigated as therapeutic agents for basal cell carcinoma, medulloblastoma and glioblastoma." (PMID 23671559, 2013). "Western blot showed that the endogenous expression of Bcl-2 was robust in both glioblastoma cell lines, while Bax expression was very weak." (PMID 24278406, 2013). "In another study the NSAID aspirin induced apoptosis by the inhibition of cyclin D1 and Bcl-2 in the A172 glioblastoma cell line." (PMID 23231886, 2012). "We found that LLL12 inhibited the transcription of the STAT3 downstream target genes, cyclin D1, survivin, Bcl-2, and Bcl-xL in medulloblastoma and glioblastoma cell lines." (PMID 21526200, 2011). "Notably, recently the assessment of BH3 mimetic Bcl-2 inhibitor has shown inhibition of tumor growth of glioblastoma in the in vivo studies." (PMID 39833890, 2025). "Given that many glioblastoma lines overexpress the antiapoptotic proteins Bcl-2 or Bcl-XL, the ability of our derivatives to overcome this resistance checkpoint via Bax insertion may prove especially valuable in treating refractory tumors." (PMID 40870991, 2025). "Totally, BCL2 inhibition by ZIKV could increase the effect of chemo/radiotherapies which makes ZIKV a great oncolytic virus in glioblastoma treatment." (PMID 39185567, 2025). "On the other hand, in addition to reducing Bcl-2 expression, the nuclear Bcl-2 suggested the alteration of the ROS homeostasis, which potentially contributes to the ferroptosis responses in radioresistant glioblastoma." (PMID 40896363, 2025). "In order to examine whether the protein stability of Mcl-1 or Bcl-2 is affected, glioblastoma cells were treated with cycloheximide in the presence or absence of the dual treatment." (PMID 38396172, 2024). "Th-ZnNPs decreased Bcl-2 expression in glioblastoma cells in a concentration-dependent manner." (PMID 39398744, 2024). "Up-regulation of miR-519a expression was found to increase glioblastoma cell sensitivity towards temozolomide—an effect achieved through promoting autophagy via dissociation of Bcl-2/BECN1 complex as well as inhibiting STAT3/Bcl-2 axis activity." (PMID 39281375, 2024). "Another study, conducted by Taylor and his colleagues (2019), demonstrated that NaB increased apoptosis in glioblastoma cells by decreasing antiapoptotic protein Bcl-2, increasing proapoptotic protein Bax, activating caspase 3, and degrading poly (ADP-ribose) polymerase (PARP)." (PMID 39200243, 2024). "Furthermore, 5-Demethylnobiletin significantly induced glioblastoma cells apoptosis by upregulating the protein levels of Bax and downregulating the protein level of Bcl-2, subsequently increasing the expression of cleaved caspase-3 and cleaved caspase-9." (PMID 37139163, 2023).
glioblastoma (continued). "In glioblastoma cells, the overexpression of anti-apoptotic proteins (Bcl-2) was observed." (PMID 36012529, 2022). "However, Dcf1 increased BECN1/Bcl‐2 ratio after 24 h, which suggested that Dcf1 preferentially drove glioblastoma cells to undergo autophagy." (PMID 34799992, 2022). "It was shown that, in the glioblastoma anti-apoptotic proteins, Bcl-2 is overexpressed." (PMID 36012529, 2022). "The miRNA-342 is elevated in glioblastoma cell, and could directly modulate BCL2 expression, suggesting a possible role in apoptosis induction." (PMID 35111757, 2021). "The miRNA-16 can promote apoptosis by targeting BCL2 in glioblastoma cell." (PMID 35111757, 2021). "Interestingly, the overexpression of antiapoptotic bcl-2 in glioblastoma cells partly compensates the proapoptotic effect of cerulenin." (PMID 34483846, 2021). "Taken together, we speculated that HMGN5 in glioblastoma cells could regulate Bcl-2, Bax, Cyclin D1, p21, MMP-2, and MMP-9 to play an oncogenic role partly via the PI3K/AKT pathway." (PMID 32596388, 2020). "The knockdown of miR-221/222 decreases Bcl2 and increases Bax in glioblastoma cells." (PMID 32489562, 2020). "ENMD-2076 could also induce apoptosis of glioblastoma cells by decreasing anti-apoptotic protein Bcl-2 and increasing pro-apoptosis proteins Cleaved Caspase-3, Bax." (PMID 31706255, 2019). "In 2016, Hao reported that miR-206 inhibited the progression of glioblastoma through BCL-2." (PMID 31798345, 2019). "Western blot analysis revealed that treating ENMD-2076 for 24h increased the expression of Cleaved Caspase-3 and Bax in LN18, T98G cells as well as decreased the expression of anti-apoptotic Bcl-2 and thereby inducing glioblastoma cells apoptosis, the ratio of Bax/Bcl-2 increased in a dose-manner." (PMID 31706255, 2019). "It was reported that miRNA-206 inhibited the progression of glioblastoma through BCL-2." (PMID 31798345, 2019). "Furthermore, the prosurvival proteins Bcl-2 and Bcl-xL have been described to be upregulated in initial and recurrent glioblastoma patients, whereas downregulation of the pro-apoptotic protein Bax has been observed." (PMID 31551765, 2019). "Additionally, miR-206 has been shown to directly target BCL2 in glioblastoma cell lines and the decreased miR-206 expression is inversely correlated with the increased BCL2 expression levels in glioblastoma tissues." (PMID 29361709, 2018). "Transduced U87MG and T98G glioblastoma cells, bearing the wild-type or mutated form of IDH1 were treated with increasing concentrations of the BH-3 mimetic ABT263, a known inhibitor of both Bcl-xL and Bcl-2." (PMID 29057925, 2017). "In this experimental study, KuA induced GBM cells apoptotic death dose-dependently, up-regulated the protein expressions of Bax and caspase-3 and down-regulated the expressions of Bcl-2 significantly in KuA treated glioblastoma cells and tumor tissues dose-dependently." (PMID 27824118, 2016). "Bcl-2 and the closely related Bcl-xL and Mcl-1 are often overexpressed in glioblastoma cells." (PMID 26775694, 2016). "This may represent a possible mechanism for glioblastoma cell apoptosis, because Bad promotes apoptosis while Bcl-2 exerts the opposite effect." (PMID 23950863, 2013). "Furthermore, the Bcl-2/Bax ratio was decrease and caspase cascade was initiated, suggesting that saponin 1 induced apoptosis in glioblastoma cells." (PMID 24278406, 2013). "In conclusion, our study demonstrated that the knockdown of hTERT effectively inhibited the cell viability of human glioblastoma cells by increasing the positive index of apoptotic cells via decreasing the expression of Bcl-2 and c-Myc and cell cycle arrest at G0/G1 phase." (PMID 22895663, 2012).
glioblastoma (continued). "Integrating new concepts of cell death reprogramming and systems-level signalling analysis, we propose that targeting the Bcl-2:beclin-1 complex and its upstream regulators could overcome the adaptive plasticity of glioblastoma multiforme and open new directions for combination treatment strategies." (PMID 41511337, 2025). "Importantly, inhibitors of Bcl-2/Bcl-xl along with Mcl-1 inhibitors in a nanoparticle format has shown efficacy in animal model system in crossing the blood-brain barrier and suppressing the growth of glioblastoma." (PMID 39833890, 2025). "Through comprehensive analysis of TCGA and CGGA datasets, we revealed that BCL2 as a G0S2-suppressed target gene that demonstrates low expression in glioblastoma (GBM)." (PMID 40519301, 2025). "Therefore, after conscientious investigation of the level and type of cell death after single and combined action of LY294002 and sorafenib in anaplastic astrocytoma and glioblastoma multiforme cells, localization changes and co-localization of Bcl-2 and beclin-1 proteins were analyzed." (PMID 38067099, 2023). "Thus, patients with glioblastoma with a reduced level of Cx43 expression have poor prognosis compared to those who present with histologically and clinically similar disease but whose neoplasm expresses high levels of Cx43 and low levels of bcl-2." (PMID 34439975, 2021). "The purpose of this study was to assess in vitro whether the biological effects of 5-aminolevulinic acid (5-ALA)-based photodynamic therapy are enhanced by inhibition of the anti-apoptotic Bcl-2 family proteins Bcl-2 and Bcl-xL in different glioblastoma models." (PMID 34439278, 2021). "In contrast, Mcl-1 is a member of the anti-apoptotic fraction of Bcl-2 proteins, which has been shown to block therapeutic responses in glioblastoma (GBM), e.g., mediating radiation resistance." (PMID 32752193, 2020). "In addition, BCL2 and Bax are key upstream regulatory factors of caspase cascade which involved in apoptosis, and regulation of BCL2/Bax expression alters proliferation and apoptosis in glioblastoma." (PMID 30420967, 2018). "In addition, because procaspase-3 is downstream in the apoptotic cascade from the typical anti-apoptotic alterations (such as Bcl-2 overexpression), this procaspase-3 elevation offers an opportunity for the selective induction of apoptotic cell death in glioblastoma." (PMID 29113289, 2017). "In the anticancer efficacy study of medicarpin on U251 and U87 glioblastoma cells, it was found that medicarpin increased apoptosis in cancer cells by increasing BAX, CYCS and CASP3 gene levels and also decreased Bcl‐2 levels." (PMID 40318008, 2025). "As a result of miRNA overexpression, the sphere formation, glioblastoma cell growth, NUMB and BCL2 protein expressions are reduced." (PMID 39185567, 2025). "Knockdown of CCND1 inhibited glioblastoma cell proliferation and invasion by simultaneously targeting multidrug resistance protein 1 (MDR1), B-cell lymphoma-2 (Bcl-2), and caspase-3." (PMID 39273281, 2024). "For example, cardamonin inhibits glioblastoma stem cell proliferation by suppressing the STAT3 pathway, which subsequently prevents the activation of Bcl-2, survivin, and VEGF." (PMID 39877386, 2024).
glioblastoma (continued). "Overexpressed miR-429 impedes glioblastoma cell growth and migration and promotes cell apoptosis by downregulating EGFR, BCL2, and MYC, which are several oncogenes of the ERBB pathway." (PMID 37854282, 2023). "The BCL-2 inhibitor ABT-737 releases pro-apoptotic BAX protein from Bcl-2 and induces apoptosis in glioblastoma cells both in vitro and in vivo." (PMID 35990696, 2022). "Based on these results, ONX-0914 treatment resulted in cell apoptosis through BCL-2 downregulation and PARP cleavage in glioblastoma cells." (PMID 36428804, 2022). "We confirmed that transfection with miR-34a resulted in a significant decrease in the protein and mRNA levels of ATM, EGFR, Bcl2, c-Met and UGCG in glioblastoma cells." (PMID 33765907, 2021). "miR-153, a brain-specific miRNA, has been reported to directly down-regulate both BCL2 and MCL1 to induce apoptosis in glioblastoma." (PMID 29361709, 2018). "Bcl2L12 is an inhibitor of the activation of postmitochondrial effector caspases that is overexpressed in glioblastoma, playing an anti-apoptotic role; it features a dominion similar to BH3 in its structure, which interacts with Bcl-xL and Bcl2." (PMID 30486451, 2018). "The present study revealed that HCMV infection blocks apoptosis in glioblastoma U87 cells and increases the expression levels of the ATF5 and Bcl-2 to BAX ratio." (PMID 25120656, 2014). "The BCL-2 inhibitor, ABT-737, was recently shown to induce apoptosis in glioblastoma cells both in vitro and in vivo by releasing the pro-apoptotic BAX protein from its binding partner BCL-2." (PMID 20515495, 2010). "Furthermore, inorganic iron oxide NPs carrying therapeutic siRNAs were efficiently used for tracking siRNA-based gene therapy targeting the BCL2 and BIRC5 of oral cancer and glioblastoma cells." (PMID 35564123, 2022). "Although untreated glioblastoma cells do not strongly express the antiapoptotic BCL2 protein, BCL2 was significantly up-regulated at 48 h when cells were treated with CRCs and at 72 h when cells were exposed to any of the carotenoids." (PMID 35739971, 2022). "Furthermore, allicin potentiates apoptosis in human glioblastoma cells, by elevating the expression of BAX and downregulating BCL2." (PMID 34422220, 2021). "Here we show that during TMZ-induced senescence in glioblastoma cells, the antiapoptotic factors c-IAP2 and Bcl-2 are responsible for the prevention of cell death and that inhibition of these factors by BV6 and venetoclax effectively kills senescent glioblastoma cells." (PMID 34298797, 2021). "Amongst the genes down-regulated by miR-34a, we selected five genes (ATM, EGFR, BCL2, MET, UGCG) for validation as they have been shown pre-clinically to play critical roles in cell survival and therapeutic resistance in the context of glioblastoma." (PMID 33765907, 2021). "The Bcl-2-inhibitor venetoclax and the c-IAP1/c-IAP2 inhibitor BV6 can enhance TMZ toxicity at early times after TMZ treatment and, most importantly, also target senescent glioblastoma cells at later times." (PMID 34298797, 2021). "Human glioblastoma cells were shown to express higher levels of BCL-2 and BCL-XL compared to non-neoplastic glial cells." (PMID 34099897, 2021). "The GRPR antagonists RC-3095, RC-3049-III, RC-3049-Et inhibited the proliferation of the human glioblastoma cell lines U-87-MG, U-373-MG, and U-118MG and in U-118MG; the tumoral expression of VEGF; the expression of PKC-alpha; and the Bcl-2:Bax ratio, indicating a net apoptotic gain." (PMID 34539578, 2021). "Our data indicate that Bcl-2 and c-IAP2 represent the core of the SCAP in TMZ-induced senescence and, therefore, point to the need for in vivo studies, targeting these factors to improve TMZ-based glioblastoma therapy." (PMID 34298797, 2021). "In glioblastomas, WT1 significantly associated poor prognostic variables: older age, negative-IDH1 status, high Bcl2 and Ki67 labelling indices (p=0.04, <0.001, =0.001 and <0.001 respectively)." (PMID 32856872, 2020).